SMCO3 (single-pass membrane protein with coiled-coil domains 3)
Synonyms: C12orf69; LOC440087
Tractability: Antibody: UniProt predicts a signal peptide or a membrane-spanning region; the Human Protein Atlas places it where antibodies can reach.
Gene: Protein-coding gene on chromosome 12 (14,804,650 to 14,814,182, reverse strand). Ensembl gene ENSG00000179256.
Subcellular location: Membrane
Subcellular location (Human Protein Atlas): Plasma membrane; Cytosol
Gene Ontology:
Molecular function: protein binding
Cellular component: membrane
Genetic constraint (gnomAD): Loss-of-function variants: 6 observed, 12.52 expected, observed/expected ratio (o/e) 0.48, 90% interval 0.26 to 0.95. The upper end of that interval is the gene's LOEUF score, 0.95, which puts it in group 4 of 6, group 1 being the genes least tolerant of losing a copy. Missense variants: 279 observed, 280.11 expected, observed/expected ratio (o/e) 1, 90% interval 0.9 to 1.1. Synonymous variants: 96 observed, 102.55 expected, observed/expected ratio (o/e) 0.94, 90% interval 0.79 to 1.11.
Homologues: Orthologues: chimpanzee SMCO3 (100% identical), macaque SMCO3 (96% identical), pig SMCO3 (94% identical), dog SMCO3 (93% identical), rabbit SMCO3 (91% identical), mouse Smco3 (85% identical), rat Smco3 (81% identical), rat Smco3l1 (81% identical), guinea pig SMCO3 (51% identical).